EPHA4 (EPH receptor A4)
Diseases named in the same sentence as EPHA4 in open-access papers (continued):
Sharing a sentence is not in itself a finding about the gene and the disease.
depression (6 papers, 2017 to 2025). "Overexpression of EphA4 in the medial PFC owing to infection with an EphA4 adeno-associated virus caused the depression-like phenotype 3 weeks later and rhynchophylline had a rapid antidepressant-like effect in these mice." (PMID 28769056, 2017). "EphA4 has also been shown to modulate synaptic plasticity, axon guidance, and neurogenesis, and all of these neural functions have previously been implicated in the pathobiology of depression." (PMID 35271507, 2022). "This is consistent with the observation that increased EphA4 signaling in the mPFC modulates brain-derived neurotrophic factor (BDNF) signaling in the social defeat mouse model of depression." (PMID 35271507, 2022). "Our work also provides the basis for new approaches to treating depression, such as by specifically inhibiting EphA4 or by promoting myelination in general as a target for future therapeutics." (PMID 35271507, 2022). "We believe our work illuminates the molecular explanation for the longstanding clinical observation that patients with MS also develop depression, and at the same time identifies EphA4 as a potential target for future antidepressant medication development." (PMID 35271507, 2022). "To further confirm that EphA4 in excitatory neurons mediates demyelination in the pathogenesis of depression, we constructed an Epha4-knockdown vector with a CaMK2a promotor to specifically knock down the expression of Epha4 in excitatory neurons." (PMID 35271507, 2022). "EphA4 knockdown prevented the depression-related behaviors in CUMS mice; sucrose preference, open field behavior, and TSTs were not significantly different than for the control mice." (PMID 35271507, 2022). "We also show the feasibility of inhibiting EphA4 specifically as a treatment strategy for depression and promoting remyelination as a more general approach to the development of new antidepressant medications." (PMID 35271507, 2022). "EphA4 knockdown prevented, and clemastine rescued, demyelination and behavior abnormalities in mouse models of depression." (PMID 35271507, 2022). "Our experiments demonstrate that EphA4 is necessary for the demyelination and synaptic deficits seen in animal models for the study of depression, and this observation is supported by convergent observational data from human brain tissue samples." (PMID 35271507, 2022). "We have demonstrated for the first time to our knowledge that increased EphA4 expression is necessary for physical or inflammatory stress to induce behaviors relevant to depression and demyelination in the mouse." (PMID 35271507, 2022). "Our data support previous associations between demyelination, oligodendrocyte dysfunction, and depression, with the additional discovery of a discrete molecular signal through EphA4 that is necessary for both the behavioral and cellular effects of the environmental stressors." (PMID 35271507, 2022). "EphA4 appears to be the crucial hub that links disparate types of depression generating insults to demyelination, synaptic dysfunction, and behaviors relevant to depression." (PMID 35271507, 2022). "Our results provide insights into the etiology of depressive symptoms in some patients and suggest that inhibition of EphA4 or the promotion of myelination could be a promising strategy for treating depression." (PMID 35271507, 2022). "To translate our findings from mouse models of depression to humans, we measured the protein levels of MBP, PSD95, and EphA4 in postmortem brain samples provided by the Stanley Medical Research Institute (Rockville, Maryland, USA)." (PMID 35271507, 2022). "However, direct evidence demonstrating the involvement of EphA4 in depression has not been published." (PMID 35271507, 2022).
ischemia (6 papers, 2013 to 2023). A hypoperfusion of the BLOOD through an organ or tissue caused by a PATHOLOGIC CONSTRICTION or obstruction of its BLOOD VESSELS, or an absence of BLOOD CIRCULATION. "Our previous studies showed that neuronal EphA4 expression was notably up-regulated after ischemia and affected post-ischemia brain damage through controlling excitatory toxicity of glutamate as well as microglia-mediated inflammatory injury." (PMID 37519758, 2023). "According to the experimental results, upregulated neuronal EphA4 induced by ischemia deteriorated neurological function as well as brain damage by shifting microglia M1-polarization via promoting NF-κB signaling." (PMID 37519758, 2023). "In summary, our study demonstrated that neuronal EphA4 up-regulation after ischemia increased inflammatory injury through promoting microglia M1 polarization." (PMID 37519758, 2023). "This research identified that neuronal EphA4 overexpression deteriorate inflammatory injury after ischemia through promote microglia M1-polarization." (PMID 37519758, 2023). "To further study the potential mechanisms of EphA4/ephrin signaling in ischemia in vitro, we applied sh-EphA4 and EphA4-OE to manipulate EphA4." (PMID 37519758, 2023). "Conversely, EphA4 knockdown promoted microglial M2 polarization and inhibited NF-κB pathway after ischemia." (PMID 37519758, 2023). "In this study, our results suggested that the blockage of upregulated neuronal EphA4 reduced post-ischemia inflammatory injury through shifting microglia M2 polarization." (PMID 37519758, 2023). "We found that EphA4/ephrin bidirectional signaling and downstream NF-κB altered microglial phenotype, and had a further impact on ischemia-induced neurological impairment and brain damage." (PMID 37519758, 2023). "Assessment of blood flow, collateral growth/remodeling and tissue necrosis following hindlimb ischemia also reveals substantial improvements in perfusion, collateral enlargement and appearance scoring in EC-specific EphA4 knockout mice." (PMID 27467069, 2016). "Inhibition of EphA4 by soluble protein inhibitors such as ephrin-A5-Fc, EphA4-Fc, or peptides induces axonal regeneration following spinal cord injury and reduces ischemia-induced apoptotic neuronal cell death." (PMID 24265799, 2013). "It is conceivable that changes in microglia polarization and neuroinflammation is the potential mechanism might explain the effect neuronal EphA4 upregulation bring on brain damage after ischemia." (PMID 37519758, 2023). "EphA4 has been shown to regulate recovery from spinal cord injury (Goldshmit, Fabes, etc refs) and may play a role in ischemia." (PMID 23390555, 2013). "First, we mainly focused on the post-ischemia inflammatory injury regulated by EphA4/ephrin signaling between neuron and microglia, but we could not exclude other possibilities, such as neuronal EphA4 might simultaneously act through astrocytic ephrin." (PMID 37519758, 2023). "EphA4 also negatively regulates EC expression of angiopoietin-1, MCP-1 and MMP2 which may have a profound effect on collateral density during development and/or remodeling following ischemia." (PMID 27467069, 2016).
lung carcinoma (6 papers, 2014 to 2025). "EPHA3 and EPHA4 reduced the development of metastasis and could possibly be useful biomarkers for prognosis in lung cancer." (PMID 35008410, 2022). "In contrast, overexpression of EPHA4 and EPHA7 is correlated with improved outcome in lung cancer." (PMID 35204461, 2022). "In both EPHA4 wild-type or EPHA4 knockout lung cancer cells, RNase1 could bind to ALK and ALK did not bind to EPHA4, which suggested that the RNase1-ALK interaction was independent of EPHA4 in lung cancer cells." (PMID 40246819, 2025).
brain trauma (5 papers, 2019 to 2025). "EphA4 has been identified as a regulator of neuroinflammation and secondary injury following brain trauma." (PMID 37461720, 2023). "While the controversial role of peripheral immune activation in brain trauma remains under investigation, our novel findings demonstrate the well-known axon guidance molecule, EphA4, is upregulated within hours of TBI and plays a substantial role in the neuro-immune milieu." (PMID 31711546, 2019).
experimental autoimmune encephalomyelitis (5 papers, 2013 to 2024). An autoimmune demyelinating disease of the central nervous system that is produced experimentally in animals by the injection of homogenized brain or spinal cord in Freund's adjuvant. "In addition, EphA4 KO mice show a less severe autoimmune phenotype than WT mice after experimental autoimmune encephalomyelitis (EAE) induction with a MOG peptide." (PMID 36334147, 2022). "Furthermore, recent data have shown that EphA4 knockout mice show a less severe clinical score after Myelin Oligodendrocyte Glycoprotein (MOG)-induced Experimental Autoimmune Encephalomyelitis (EAE) compared with wild-type animals." (PMID 26354550, 2015).
lung adenocarcinoma (5 papers, 2014 to 2021). A carcinoma that arises from the lung and is characterized by the presence of malignant glandular epithelial cells. "Another study analyzing 11 Ephs and 8 ephrins, indicated that EphA4 and ephrin-A1 gene expression was associated with improved lung adenocarcinoma patients’ outcome, possibly by affecting cancer cell migration and invasion." (PMID 24495444, 2014). "In contrast, EphA4 reduces tumour cell migration and invasion in lung adenocarcinoma through EphA4-dependent ERK1/2 inactivation." (PMID 33741023, 2021). "Among these were mutations in two well-known ccRCC cancer driver genes (VHL and PBRM1) and in EPHA4, a lung adenocarcinoma driver gene." (PMID 31212796, 2019). "This is also supported by recent studies that showed inhibition of invasion and tumor growth by EPHA7 in follicular lymphoma and by EPHA4 in lung adenocarcinoma." (PMID 27095580, 2016). "Squamous cell lung carcinoma patients showed a no significant increased incidence of moderate/high EphA4 compared to those with adenocarcinoma, while moderate/high EphA5 and A7 expression was more frequently observed in lung adenocarcinoma patients compared to those with squamous cell carcinoma." (PMID 24495444, 2014).
lymph node metastasis (5 papers, 2013 to 2025). "Our study also linked high EPHA4 expression with the presence of lymph node metastasis and high EPHA7 expression with a higher nuclear grade of tumor cells, both at no significant level though." (PMID 35204461, 2022). "Moderate/high EphA4 expression was significantly associated with low stage and presence of inflammation and borderline with lymph node metastases." (PMID 24495444, 2014). "EPHA4 overexpression was associated with lymph node metastasis in TNBC patients (p = 0.0546)." (PMID 35204461, 2022). "High EPHA4 expression was observed more frequently in TNBC cases accompanied by lymph node metastasis (p = 0.0546), although insignificantly." (PMID 35204461, 2022). "Our results also showed that lymph node metastasis was the strongest prognostic factor, and EphA4 was the second most significant prognostic factor in PDAC compared with the other clinicopathological factors." (PMID 26516928, 2015). "Similarly, elevated EphA4 expression was significantly associated with the absence of lymph node metastases." (PMID 40421081, 2025). "Elevated EphA4 expression was significantly associated with the absence of lymph node metastases." (PMID 40421081, 2025).
multiple sclerosis (5 papers, 2012 to 2022). A progressive autoimmune disorder affecting the central nervous system resulting in demyelination. "It is interesting to note that EphA receptors were found to be upregulated in active lesions of multiple sclerosis patients, suggesting that EphA4 upregulation is associated with demyelination." (PMID 31798398, 2019). "In the CNS, inflammatory cells in lesions from multiple sclerosis patients were found to express EphA4, as well as a number of other Ephs and ephrins." (PMID 22629434, 2012). "Although there is no available evidence that proved the function of EPHA4 in the pathogenesis of SLE, EPHA4 as a possible inflammatory mediator may contribute to the immunopathological disease like multiple sclerosis and neuropsychiatric disorder in SLE." (PMID 35462789, 2022).
Cognitive impairment (4 papers, 2014 to 2023). Abnormal cognition is characterized by deficits in thinking, reasoning, or remembering. "The Eph receptor A4 is highly expressed in human adult hippocampal brain tissue and was previously linked to cognitive impairment in a transgenic mouse model for AD." (PMID 25027113, 2014). "Limitation of downstream effects of EphA4 signaling in neurons could attenuate cognitive impairment associated with Aβ‐induced neurodegeneration in AD." (PMID 36494892, 2023).
Parkinson disease (4 papers, 2011 to 2025). A progressive degenerative disorder of the central nervous system characterized by loss of dopamine producing neurons in the substantia nigra and the presence of Lewy bodies in the substantia nigra and locus coeruleus. "In the regulation of inflammation, HOXA11-AS mediated CaOx crystal-induced renal inflammation via the miR-124-3p/MCP-1 axis, while inhibition of HOXA11-AS repressed neuroinflammation and neuronal apoptosis in Parkinson’s disease model through through miR-124-3p-FSTL1-NF-κB axis and miR-98-5p/EphA4." (PMID 38902760, 2024).
spinal cord injury (4 papers, 2011 to 2022). Penetrating and non-penetrating injuries to the spinal cord resulting from traumatic external forces (e.g., WOUNDS, GUNSHOT; WHIPLASH INJURIES; etc.). "Erythropoietin-producing hepatocyte A4 (EphA4) not only plays a guiding role in neurite outgrowth during the development of the central nervous system (CNS) but also induces injured axon retraction and inhibits axon regeneration after spinal cord injury (SCI)." (PMID 33595805, 2022).
adenoma (3 papers, 2018 to 2020). A neoplasm arising from the epithelium. "The last four genes in our study were downregulated in carcinoma compared to adenoma, and those are EPHA4, KIAA1324, L1TD1, and PCKS1." (PMID 30175151, 2018). "Immunohistochemistry for EPHA4 showed positive reaction in epithelial cell in both adenoma and AEM, but the reaction in the stroma was mild in adenoma, and more intensive in AEM." (PMID 33322258, 2020). "The difference in expression between adenoma and AEM was only significant for EPHA4 (p < 0.001) and FN1 (p = 0.009)." (PMID 33322258, 2020). "Expression of EPHA4 was also up-regulated in AEM, while expression of other genes in AEM showed down-regulation to a lesser extent than in adenoma." (PMID 33322258, 2020). "EPHA4 and L1TD1 follow the third pattern, which higher expression in adenoma and lower in normal and carcinoma." (PMID 30175151, 2018). "The aim of this study was to determine whether the expression of selected ECM-related genes (DCN, EPHA4, FN1, SPARC, SPON2, and SPP1) was similar in adenoma and AEM but differed from the expression in AEC and advanced carcinoma." (PMID 33322258, 2020). "Compared to non-tumoral pituitary, EPHA4 was 51.5, 5.25, and 3.03 times more up-regulated in ACTH-secreting tumors, TSH, PRL and GH-secreting adenomas and non-functioning adenomas, respectively (p = 0.0001)." (PMID 33168897, 2020).
breast tumors (3 papers, 2017 to 2023). "On the basis of our findings, we present a model showing an unconventional role of hRNase 1 as a secretory ligand of EphA4 that induces breast tumor initiation." (PMID 33986289, 2021). "In addition, analysis of human breast tumor tissue microarrays reveals a positive correlation between hRNase 1, EphA4 activation, and stem cell marker CD133." (PMID 33986289, 2021).
diffuse large B-cell lymphoma (3 papers, 2020 to 2025). "Interestingly, EBV LMP1 is a known regulator of EphA4 expression, and an inverse correlation of EBV infection and EphA4 expression was observed in EBV+ and EBV− diffuse large B-cell lymphoma (DLBCL) and EBV− tonsils compared to EBV+ posttransplant lymphoproliferative disorder." (PMID 40501621, 2025).
endometritis (3 papers, 2024 to 2025). An acute or chronic, usually bacterial infectious process affecting the endometrium. "Gene expression levels were considerably higher in endometritis-affected buffaloes than in resistant ones for the genes A2M, TLR2, IRAK3, CCl2, FCAMR, iNOS, ADAMTS20, KCNT2, MAP3K4, MAPK14, FKBP5, and EPHA4." (PMID 38459095, 2024).
hepatocellular carcinoma (3 papers, 2014 to 2025). A malignant tumor that arises from hepatocytes. "Studies have found that EPHA4 mediates the EMT process of human hepatocellular carcinoma by downregulating the expression of E-cadherin and vimentin." (PMID 24932309, 2014).
medulloblastoma (3 papers, 2015 to 2025). A malignant, invasive embryonal neoplasm arising from the cerebellum. "In medulloblastoma, elevated expression of EphB1 and EphA4 is associated with enhanced angiogenesis and migratory capacity, contributing to tumor progression." (PMID 41200151, 2025). "In the present study, we sought to determine the effects of loss of ephrin-A5 and the EphA4/EphA7 receptor pair on medulloblastoma tumor growth in vivo." (PMID 26345456, 2015). "In the present study, we investigated the effects of genetic loss of ephrin-A5, EphA4, and EphA7 on the spatiotemporal development of medulloblastoma tumors in the context of the smoothened transgenic mouse model system." (PMID 26345456, 2015). "EphA4 expression is consistently reduced in medulloblastoma cell lines compared to normal brain tissue." (PMID 41200151, 2025). "Our findings highlight the necessity to further confirm a relation of VAPB protein expression and EPHA4 phosphorylation status in primary human medulloblastoma samples." (PMID 37945695, 2023). "We indeed found that EPHA4 gene expression was significantly decreased in medulloblastoma samples compared to unaffected tissue in each data set." (PMID 37945695, 2023). "From these data, we conclude that downregulation of EPH4A protein or inactivation of EPHA4 through inhibiting its phosphorylation both promote medulloblastoma growth in a 3D setting." (PMID 37945695, 2023). "We first assessed the expression patterns of EPHA4 in medulloblastoma." (PMID 37945695, 2023). "To test whether this interaction also exists in medulloblastoma cell lines, we used our previously generated medulloblastoma cell lines expressing HA-tagged VAPB and performed co-immunoprecipitation as well as PLA assays using HA and EPHA4 as bait." (PMID 37945695, 2023). "Genetic alteration of EphA4/EphA7 yields no consistent effect on tumor size in the Smo/Smo mouse medulloblastoma model." (PMID 26345456, 2015). "As we could not find evidence for a direct interaction between VAPB and EPHA4, in medulloblastoma cells, we then investigated whether the absence of VAPB would affect the expression or phosphorylation of EPHA4." (PMID 37945695, 2023).
pancreatic adenocarcinoma (3 papers, 2015 to 2022). "However, increased EPHA4 expression has been associated with an unfavorable prognosis in a few tumor types, such as in gastric adenocarcinomas, whereas knocking down EPHA4 expression in pancreatic adenocarcinomas has been associated with decreased proliferating capacity." (PMID 35626181, 2022). "Ephrin receptor A4 (EphA4) is overexpressed in human pancreatic adenocarcinoma (PDAC) and activate cell growth." (PMID 26516928, 2015). "Similarly, EphA4 has been reported to be upregulated in pancreatic adenocarcinoma cell lines; interestingly, knocking down EphA4 expression was associated with decreased proliferating capacity, highlighting its potential as a therapeutic target." (PMID 34943502, 2021).
bladder cancer (2 papers, 2017 to 2022). "Thus, it was very essential to explore the correlations among FGFR3, KIAA1377, POLA2, and EPHA4 in bladder cancer, as well as other cancers or diseases." (PMID 28320388, 2017). "EphA2 is the key mediator of progranulin signaling in bladder cancer where progranulin did also modestly activate EGFR, EphA4 and EphB2." (PMID 36471440, 2022).